CXCL2 (C-X-C motif chemokine ligand 2)
Diseases named in the same sentence as CXCL2 in open-access papers (continued):
Sharing a sentence is not in itself a finding about the gene and the disease.
infection (continued). "Indeed, in vivo, a complex network of soluble (e.g., chemokine gradients) and solid (e.g., ECM proteins, epithelial cells) cues guides maturation and migration of neutrophils from the BM to sites of infection, with the chemokines CXCL1 and CXCL2 being the most potent neutrophil attractants in vivo." (PMID 40467528, 2025). "Macrophages migrate to the infection site via chemotaxis, where they recognize and phagocytize fungal pathogens while producing various pro-inflammatory cytokines and chemokines, including TNFα, CXCL1, CXCL2, CCL2, and IL-1β, thereby promoting inflammation and immune defense." (PMID 41190069, 2025). "Moreover, CCL2, CCL21, CXCL2, CXCR2, and CXCR3 mRNAs were significantly induced at 6–12 h after V. harveyi infection, implying that P. leopardus immune cells can be activated and recruited to the sites of infection at early time points post-infection." (PMID 39450165, 2024). "Moreover, increased serum levels of CXCL1 and CXCL2, as potent chemo-attractants for neutrophils mobilization via their sole receptor CXCR2, can recruit neutrophils from peripheral circulation to the focus of infection." (PMID 36369287, 2022). "Similarly, chemokines (e.g. CXCL1, CXCL2, and CXCL5) that play a pivotal role in neutrophil recruitment to sites of infection and injury were induced 2–3 orders of magnitude, whereas CXCL12/SDF‐1 and adhesion G‐protein coupled receptor F5 (ADGRF5, GPR116) expression was unaffected." (PMID 36151614, 2022). "Compared to virulent MERS-CoV-MA-WT and MERS-CoV-MA-mNLS infection, attenuated MERS-CoV-MA-Δ4b induced, either at 4 or 6 dpi, lower levels of CCL2, CCL4 and CXCL10, which are monocyte and macrophage chemoattractants, and CXCL1 and CXCL2, which are neutrophil chemoattractants." (PMID 36129908, 2022). "This infection is generally characterized by inflammatory cytokines interleukin-1 beta (IL-1β), tumor necrotizing factor alpha (TNF-α), interleukin-6 (IL-6), chemokine (CX-C motif) ligand 2 (CXCL2), and IL-8 (also known as chemokine (CX-C motif) ligand 8-CXCL8)." (PMID 35053737, 2022). "In the mutant strain infection, we noted that Th17-related cytokines (IL-17A, IL-22) and neutrophil-related chemokines (CCL2, CCL3, CXCL1, CXCL2) are significantly reduced at the early stage of infection, which might be related to the absence of melanin and defects in growth and germination." (PMID 35696422, 2022). "To identify mechanistic bases for the different numbers of neutrophils at the site of infection, we measured the main chemokine factors for neutrophil attraction, including the CCR1 ligands CCL3, CCL4, and CCL5 and the CXCR2 ligands MIP-2/CXCL-2, KC/CXCL-1, and CXCL5." (PMID 32424099, 2020). "Expression of an array of cytokines (CSF3 [G-CSF], IFNγ, IL-1β, IL-6, IL-22, IL-17A, and IL-10), chemokines (CCL20, CXCL2 and CXCL9) and receptors (CD40) known to be involved in the regulation of S. pneumoniae inflammatory response was measured at 0, 6, 24, and 48 h post-infection." (PMID 30333823, 2018). "We further examined the gene expression of pro-inflammatory chemokines (CXCL1, CXCL2 and CCL2), chemokine receptor CCR7, and TLR4 in lung tissues in order to determine the potential mechanism(s) of immune cells infiltration into the lungs of newborns following low dose infection with B. pertussis." (PMID 28798335, 2017). "After KEI 1025 infection, GLY treatment reduced HMGB1 (mRNA and protein levels) and improved disease outcome with significant reduction in mRNA levels of IL-1β, TLR4, CXCL2, and IL-12; protein expression (IL-1β, CXCL2); neutrophil infiltrate; and bacterial load." (PMID 27792814, 2016). "Furthermore, Pkcδ-deficient macrophages produced higher amounts of IL-1α and CCL5, but not CXCL2 than WT macrophages in response to infection." (PMID 24516390, 2014).
infection (continued). "Owing to their strategic location in close proximity to the site of infection, tissue-resident macrophages are upon the primary inducers of an inflammatory reaction and as such promote the egress of neutrophils from the circulation by secreting chemokines including CXCL1 and CXCL2." (PMID 24755316, 2014). "As neutrophils are massively recruited during PVM infection, chemokine KC (CXCL-1) and MIP-2 (CXCL-2) - two major chemokines involved in neutrophils recruitment in mouse - were measured in the BALF of P2Y2+/+ and P2Y2−/− mice by ELISA at days 8, 9, 10 and 12 post-infection." (PMID 23185614, 2012). "Furthermore, transcriptional profiling of hBMEC during infection with B. anthracis revealed downregulation of 270 (87%) genes, specifically key neutrophil chemoattractants IL-8, CXCL1 (Groα) and CXCL2 (Groβ), thereby strongly contrasting hBMEC responses observed with other meningeal pathogens." (PMID 18698416, 2008). "Similarly, the chemokines CCL2 (attracting monocytes), CXCL2 (attracting neutrophils), CCL5 (attracting T cells), CXCL10 (attracting activated T cells, eosinophils), and CCL11 (eosinophils) were elevated during infection with a significant reduction in TLR7 KO mice." (PMID 39769461, 2024). "Notably, compared with S. aureus-infected WT mice, similarly infected RBP-J CKO mice had lower percentages of splenic neutrophils at 3, 6, and 24 h post-infection, suggesting that CXCL1/CXCL2 released by MZ B cells may recruit neutrophils in the early phase of systemic S. aureus infection." (PMID 34040603, 2021). "Similarly, CXCL1 and CXCL2 quickly increased in the early stages of GBS infection, while a significant difference in these two factors in WT and Fpr2-/- can be detected at 1 hour and 3 hours for both i.v. and i.p. infection route, which is consistent with that of the neutrophils increase." (PMID 34899755, 2021). "Besides chemokines, cytokines such as TNF-α are released acutely in response to injury or infection, and function to initiate and maintain the inflammatory process in part by stimulating other pro-inflammatory cytokines (e.g., IL-1α, IL-1β, and IL-6) and chemokines (e.g., CCL2, CCL3, and CXCL2)." (PMID 26860080, 2016). "We observed that a number of NF-κB inducible genes were significantly elevated at 4 weeks post-infection (but not at 2 weeks) by qRT-PCR in B6 miR-146a−/− joints, compared to WT, including cytokines IL-1β and IL-6, as well as neutrophil chemokines Cxcl1 and Cxcl2." (PMID 24967703, 2014). "Similarly, a number of chemokines known to recruit leukocytes to infection sites were upregulated by MØs and DCs during Bb infection, but many of these were suppressed in the presence of Bb-elicited IL-10, particularly the neutrophil-recruiting chemokines such as KC (CXCL1) and MIP-2α (CXCL2)." (PMID 24367705, 2013). "Importantly, a higher number of Cxcl-2+ activated cells as compared to Listeria-infected cells was observed by flow cytometry after infection with both reporter constructs and epithelial Cxcl-2 synthesis was similarly noted in Listeria-negative epithelial cells." (PMID 21124989, 2010). "Overall, our findings suggest that during infection in the absence of IL-27 signaling, a differential expression of CXCR2 and CXCL2 promotes increased migration of mononuclear cells consistent with improved bacterial clearance and tissue homeostasis." (PMID 40977737, 2025). "At early time points, Fpr2-/- mice showed a significant decrease in CXCL1, CXCL2, IL-1β, CCL2, GM-CSF, IL-6, and CCL3 levels at 1 hour and 3 hours after infection, and an increase in IL-22 and IL-23, but there is no change in TNF-α, as compared with WT mice." (PMID 34899755, 2021). "For instance, both the CXCL2 chemokine and the mycobacteria receptor syndecan 4 SDC4 were significantly upregulated after PCLS infection with AF2122, Mb3601, or H37Rv in Blonde d'Aquitaine, but not in Charolaise." (PMID 34307535, 2021).
infection (continued). "Although there was a modest increase of XCL1, CCL2, CXCL2 and CXCL10 mRNAs in these mice following infection, this was not statistically significant." (PMID 32310998, 2020). "In contrast, we observed significantly enhanced expression of Cxcl1 (KC), Il6, and Il17, but not of Cxcl2 (MIP-2), Ifng, or Il10, in the huLangerin group as opposed to WT controls after infection with the S. aureus ΔtarM mutant." (PMID 31088921, 2019). "The concentrations of all cytokines and chemokines in the spleen 20 hours after infection (IL-6, IL-10, CXCL1, and CXCL2) were not different among all three groups studied." (PMID 25563481, 2015). "Also, TNF levels in BALF were significantly lower in Lysmcre-Btkfl/Y mice as compared to controls (p<0.05) 3 hours after D39 infection, whereas IL-6, CXCL1 and CXCL2 levels were not altered." (PMID 34552589, 2021). "However, it appeared that in the DKA mouse model, the infection induced more inflammatory cytokines and chemokines involved in neutrophil (CXCL1) and macrophage (CXCL2) recruitment vs. uninfected mice and regardless of the mouse gender." (PMID 33919611, 2021). "In our data, neutrophil recruitment to infection site, in ethanol-fed mice, was impaired even though we did not observe decrease in both CXCL1 and CXCL2 BALF levels, indicating that ethanol consumption is responsible for compromising neutrophils activation and migration." (PMID 32701055, 2020). "Our results showed that topical LTB4 decreased lesion size and bacterial clearance in macrophage-depleted mice, restored production of the chemokines, CCL2 and CXCL4, but not CXCL2, VEGF, IL-33, and IL-1β and neutrophil migration to the site of infection in DT-treated MMDTR mice." (PMID 30102746, 2018). "However, there were no HIF-1α-dependent differences in lung cytokine secretion, indicating that lung epithelial HIF-1α is not required to induce IL-1β, IL-6, CXCL1, CXCL2, or MIP-3α secretion during infection." (PMID 27624128, 2016). "While IL-17R KO animals predictably had significantly higher amounts of IL-17 in brain abscess homogenates, several other mediators were also elevated between 7 and 14 days after infection, including IL-1α, IL-1β, IL-6, CCL3 and CXCL1 (data not shown), as well as CXCL2 and CXCL9." (PMID 22704602, 2012). "The number of Listeria-induced Cxcl-2+ cells, however, was not altered irrespective whether BFA was administered 30 min prior or 60 min after infection." (PMID 21124989, 2010).
cancer (205 papers, 2011 to 2026). A tumor composed of atypical neoplastic, often pleomorphic cells that invade other tissues. "Differential analysis between high-risk and low-risk cancer cells revealed that high-risk cancer cells exhibited elevated expression of genes associated with M2 macrophages, including CXCL2, IL6R, CXCL8, GDF15, CD68, and PTX3." (PMID 41034991, 2025). "We also explored the expression of the underlying cancer‐promoting genes within cluster 3; these genes included Cdkn1a, Plaur, Ptgs2, Cox17, Lilrb4q, G0s2, Egr1, and Cxcl2, with previous reports suggesting their implication in increasing cancer progression." (PMID 39113226, 2024). "CXCL2 is a pro-inflammatory factor which is associated with biological signs of progress, such as angiogenesis, inflammation and cancer." (PMID 37696876, 2023). "A curcumin-dependent downregulation of the chemokines C-X-C motif chemokine ligand (CXCL)-1 and CXCL-2 in cancer cells was observed, which was influenced by NF-κB, a transcription factor associated with inflammation and cancer progression." (PMID 35631330, 2022). "TNF-alpha increases CXCL1 and CXCL2 expression in cancer cells and amplifies the CXCL1/2 S100A8/9 loop, which causes chemoresistance." (PMID 25562519, 2013). "Elevated levels of cytokines such as tumor necrosis factor alpha (TNF-α), interleukin (IL)-6 and IL-1β, a lipid molecule prostaglandin E2 (PGE2), and chemokines such as CXC chemokine ligand 1 (CXCL1) and CXCL2 in the serum of CRC patients were associated with cancer development and progression." (PMID 35954156, 2022). "Interestingly, a recent report also showed that IL-8, CXCL1, and CXCL2 secreted by cancer-associated mesenchymal stromal cells can promote the polarization of TAMs." (PMID 36411463, 2022). "In addition to that, CXCL2 was also found to be involved in cancer-associated bone destruction." (PMID 24405819, 2013). "The overexpression of CXCL1 and CXCL2 in cancer cells has been shown to attract neutrophils into tumors, leading to chemoresistance, a process that can be mitigated by blocking CXCR2." (PMID 41486114, 2026). "In terms of immune regulation, CXCL2 is involved in a variety of immune responses, including wound healing, cancer metastasis, and angiogenesis." (PMID 41378129, 2025). "As our findings showed that Vox strongly reduced neutrophils in tumors, we analyzed the expression of Cxcl1, Cxcl2 and Cxcl5 (genes encoding neutrophil-recruiting chemokines) in FACS-sorted cancer cells, total immune cells, neutrophils and macrophages." (PMID 40139833, 2025). "Then, gene silencing in cal27 cells was used to evaluate the role of CXCL2 in the Fn-pro-cancer effect and Fn-amplifying macrophage recruitment and M2 polarization effects." (PMID 38637499, 2024). "CXCR-2 ligands include CXCL-1, CXCL-2, CXCL-3, CXCL-5, IL-6, CXCL-7 and IL-8, and overall CXCLs/CXCR-2 pathway is implicated in cancer and inflammation." (PMID 38672477, 2024). "To explore how 14-3-3ζ+++ cancer cell-secreted CXCL2/5 induce Cox2 expression in PSCs/fibroblasts, we profiled fibroblasts cultured in CM (10% FBS or 0% FBS) of Panc02.shCtrl cells or Panc02.shζ cells by RPPA." (PMID 39468013, 2024). "These receptors are activated by multiple signaling molecules including CXCL-1, CXCL-2, CXCL-5, CXCL-8, and IL-8 released by various constituents of this environment, including cancer cells, immune cells, and cancer-associated fibroblasts." (PMID 38361931, 2024). "CXCL2, a member of the CXCL chemokine family, plays a significant role in inflammatory responses, closely associating inflammation and cancer." (PMID 39770551, 2024). "Functional analysis data indicated that the addition of recombinant human CXCL2 significantly enhanced the migration and invasion abilities of cancer cells while impairing their adhesion ability." (PMID 37686542, 2023). "This suggests that genes in our signature have an impact on the physiological processes of cancer cells, especially the CXCL2 and CX3CL1 genes." (PMID 37021054, 2023).
cancer (continued). "Neutrophils can also accumulate in the metastatic niche, where the expression of G-CSF, CXCL1, and CXCL2 by cancer cells and stromal cells promote their recruitment." (PMID 37444436, 2023). "A few studies signify the role of CXCL2 in promoting the progression and metastasis of cancer, including prostate, by inducing TAMs, recruitment of MDSCs, and suppression of CD8 T cell accumulation via CXCL2-CXCR2 signaling." (PMID 37698493, 2023). "Thirdly, CXCL2 was found to directly enhance the malignant features of carcinoma cells such as proliferation, invasion, and migration." (PMID 37540227, 2023). "CXCL2 related to neutrophil response under various conditions such as wound healing, cancer metastasis and angiogenesis." (PMID 35452485, 2022). "The CXC chemokines (e.g., CXCL1, CXCL2, CXCL3, CXCL5, and CXCL8) are significantly upregulated in most cancers and positively associated with cancer metastasis and chemo-resistance." (PMID 36612163, 2022). "We then developed a new gene therapy against cancers by combining CXCL2 plasmid DNA and HVJ-E (C/H)." (PMID 33575480, 2021). "Then, cell viability assays showed that CXCL2 overexpression remarkably promoted cancer cell chemoresistance in cisplatin-sensitive EOC cells." (PMID 34474677, 2021). "To investigate the mechanisms that altered migration and invasion of gastric cells, we evaluated the expression of cytokines CCL20, CCL28, and CXCL-2, which promote the migration and invasion of various cancer cells." (PMID 33194715, 2020). "Recently, we demonstrated that the MDSC in premetastatic organ secreted the proinflammatory chemokine, chemokine (C-X-C motif) ligand 2 (CXCL2) to attract C-X-C motif chemokine receptor 2 (CXCR2)-expressing cancer cells." (PMID 32170086, 2020). "The expression of CXCL1, CXCL3, CXCL2, CCL20, and IL6 are enriched in residual cancer and are associated with lesser response the chemotherapy when highly expressed at baseline." (PMID 30967156, 2019). "Most members of the chemokine family, including CXCL1, CXCL2, CXCL5, CXCL9, CXCL10 and CXCL13, where they are secreted by cancer or stromal cells, such as cancer-associated fibroblasts (CAFs) and dendritic cells (DCs)." (PMID 30925930, 2019). "CXCL2 knockdown results showed reduced expression of cancer stem cell proteins, cyclins, and EMT markers, mediating through Gαi-2 and Gαq/11 to promote tumorigenesis." (PMID 31781593, 2019). "CXCL2 is an important cytokine, which usually is involved in wound healing, cancer metastasis, apoptosis, and angiogenesis." (PMID 30871526, 2019). "Intratumoral CXCL2 also attracts granulocytes, that in turn, boost cancer cell survival and angiogenesis, by releasing additional chemokines." (PMID 30591657, 2018). "BLC2 (which was downregulated) and BCL2L1 are anti-apoptotic; IL8 and CXCL2 are chemokines that are pro-inflammatory and enhance the proliferation and survival of cancer cells." (PMID 29188362, 2018). "Our study showed that doxycycline suppressed both LPA- and TNFα-induced nuclear translocation of NF-κB and blocked the LPA-induced secretion of IL-6, CCL2 and CXCL2 in cancer cells." (PMID 28178994, 2017). "Since CXCL2 is required for CRT induction in cancer cells, we investigated the levels of murine chemokine CXCL2(KC) in Mtb-infected murine macrophages." (PMID 28938588, 2017). "For example, over-expression of CXCL1 and CXCL2 favors cancer cell survival in metastatic sites through the induction of S100A8 and S100A9 secretion from CD11b+Gr1+cells." (PMID 28429725, 2017). "These networks are interconnected with a subnetwork of genes that are associated with cancer progression, such as COX2, TGFβ, CCL2, CXCL2, MMP9, and MMP13." (PMID 26831400, 2016). "The MB-downregulated genes include cancer-associated cytokines/chemokines (e.g. CXCL1, CXCL2, CXCL3, CXCL14, IL1A, IL1B, IL6, IL8) and matrix metalloproteinases (MMP1,MMP9)." (PMID 25642713, 2015).